PRF1 (perforin 1)
Diseases named in the same sentence as PRF1 in open-access papers (continued):
Sharing a sentence is not in itself a finding about the gene and the disease.
cutaneous melanoma (8 papers, 2018 to 2022). A primary melanoma arising from atypical melanocytes in the skin. "In TCGA-ACC, skin melanoma, and bladder cancer, CYT was associated with an improved patient outcome and high levels of both GZMA and PRF1 synergistically affected patient survival in these cancers." (PMID 29515971, 2018). "TMBhigh skin melanomas also correlate with intratumoral immune cytolytic activity (CYT), defined by the expression of granzyme A and perforin 1, both secreted by effector cytotoxic CD8+ T-cells and NK cells against their target cells." (PMID 36389735, 2022). "To determine whether CYT-high is a good prognostic indicator, we explored the overall survival of skin melanoma patients having high or low expression levels of GZMA and PRF1, using SynTarget." (PMID 33779796, 2021). "In addition, the correlation between IL32 and various genes of cytolytic molecules, such as GZMA, GZMB, and PRF1, is positive, suggesting that IL32 mRNA expression may increase patient survival through the infiltration and activation of anticancer effector cells in cutaneous melanoma." (PMID 34682815, 2021).
lung carcinoma (7 papers, 2021 to 2025). "In addition, we demonstrated that CD8+ T cells in a patient with lung cancer exhibited lower expression of cytotoxic marker PRF1 and activation marker CD69 in co-cultured with A549 for 24 h compared to a healthy volunteer." (PMID 36688994, 2023). "Although we found that both perforin and granzyme B were significantly less expressed at mRNA level in patients with lung cancer, PRF1, but not GRZMB, positively correlated with SPI1 mRNA expression in both cohorts." (PMID 40895524, 2025). "High expression of the BC-specific ICD-derived metagene signature (TNF/CXCR3/P2RX7/CASP1/NLRP3/IL1B/LY96/CD4+/CD8+A/CD8+B/PRF1/IFNG/IL17A/IL17RA) is associated with prolonged overall survival (OS) in BC and OC patients but not in lung cancer patients." (PMID 37445860, 2023). "The activation markers GZMB, PRF-1, and IFNγ, migration marker CD183 (CXCR3), and inhibitory marker CD274 (PD-1), were measured and compared in CD8+ T cells with A549 co-cultured, chemokines treated, and patients with late-stage lung cancer." (PMID 34680466, 2021).
colorectal cancer (6 papers, 1991 to 2025). A primary or metastatic malignant neoplasm that affects the colon or rectum. "PRF1-rs10999426 has been clustered with other genes associated with cytotoxic T cells in a colorectal cancer study: high expression of the cytotoxic cluster genes was associated with a prolonged disease-free survival." (PMID 24391818, 2013). "Transcripts specific to co-stimulatory molecules (CD80 and CD86), HSP60, MHC peptides, pro-inflammatory cytokine receptors, Perforin 1 and Caspase 9 were amongst those that were up-regulated in MSI-H colorectal cancers." (PMID 15298707, 2004).
malaria (6 papers, 2005 to 2026). Malaria is a serious and sometimes fatal disease caused by a parasite that commonly infects a certain type of mosquito which feeds on humans. "The immunity related genes that are down-regulated in the malaria severity signature are: PRF1, GNLY, OAS2, MX1, OAS3 and CCL5." (PMID 29642892, 2018). "Similarly, in malaria these genes were either only modestly upregulated (GZMA and GZMB) or were downregulated (GZMH, GNLY and PRF1), compared to HS (P < .05)." (PMID 33793565, 2021).
hepatocellular carcinoma (5 papers, 2019 to 2024). A malignant tumor that arises from hepatocytes. "In HCV-infected human hepatocellular carcinoma cells, PRF1 encodes perforin, which plays an important role in the lysis of CD8+ T cells." (PMID 39199299, 2024). "Enhancement of NK cell cytotoxicity with upregulation of Prf1 was described as associated with miR-182 overexpression in NK cells derived from hepatocellular carcinoma (HCC) patients." (PMID 32161759, 2020). "A key factor in lysogenic cell death, PRF1, has been identified as an important target in the treatment of hepatocellular carcinoma." (PMID 39199299, 2024). "Several studies have demonstrated that PRF1 plays a significant role in determining the prognosis of hepatocellular carcinoma (HCC) and predicting disease recurrence, especially after liver transplantation." (PMID 39199299, 2024). "In addition, five immune-related genes (IRGs)-FABP6, CD4, PRF1, EREG, and COLEC10-associated with the tumor microenvironment (TME) were significantly predictive of recurrence-free survival (RFS) and overall survival (OS) in patients with hepatocellular carcinoma." (PMID 39199299, 2024). "In NK cells of hepatocellular carcinoma (HCC) patients it was suggested that miRNA-182 may augment NK-cell cytotoxicity against liver cancer through perforin-1 up-regulation and by modulating NKG2D and NKG2A expressions." (PMID 30939820, 2019).
immune deficiency (5 papers, 2018 to 2025). "PRF1 germline mutations have been associated with an autosomal recessive immune deficiency, familial hemophagocytic lymph histiocytosis of type 2 and childhood anaplastic large cell lymphoma (ALCL)." (PMID 36271373, 2022). "FHL2 is a fatal immunodeficiency condition, caused by PRF1 gene mutations exhibiting manifestations in immune cells that lead to systemic inflammation and multiorgan failure." (PMID 30021624, 2018).
influenza (5 papers, 2016 to 2021). An acute viral infection of the respiratory tract, occurring in isolated cases, in epidemics, or in pandemics; it is caused by serologically different strains of viruses (influenzaviruses) designated A, B, and C, has a 3-day incubation period, and usually lasts for 3 to 10 days. "The top five genes of each of the two clusters (NK cell activity; NK and T‐cell activity) that were most closely correlated with influenza antibody titers had seven genes (SPON2, AKR1C3, PRF1, FCRL6, GZMA, CSTK, NKG7) which belong to the aging signature genes of IL‐7Rαlow EM CD8+ T cells." (PMID 31044512, 2019).
leukemia (5 papers, 2017 to 2023). A malignant (clonal) hematologic disorder, involving hematopoietic stem cells and characterized by the presence of primitive or atypical myeloid or lymphoid cells in the bone marrow and the blood. "Mutations and variants in PRF1 gene are also documented in other disorders which include perforin deficiency, multiple sclerosis, type 1 diabetes, Non-Hodgkin lymphoma, and leukemia." (PMID 28468610, 2017). "Finally, altered expressions of CD28, CCR7, CX3CR1, IFNG, LTB and PRF1 were all contributing to the inflammatory profile of the TCRγδ+ T-LGL leukemias." (PMID 28407008, 2017).
lung adenocarcinoma (5 papers, 2018 to 2025). A carcinoma that arises from the lung and is characterized by the presence of malignant glandular epithelial cells. "Lastly, although the authors observed inverse correlations between EPHA2 and CTL gene signatures in human pancreatic cancer, we did not discover any consistent trends between EPHA2 and CD3E, CD8B, GZMA, GZMB, PRF1, or IFNG expression from the TCGA lung adenocarcinoma dataset." (PMID 40867322, 2025).
acute lymphoblastic leukemia (4 papers, 2014 to 2025). Leukemia with an acute onset, characterized by the presence of lymphoblasts in the bone marrow and the peripheral blood. "The PRF1 rs885822 (G/A) were found associated with susceptibility to multiple sclerosis, survival in childhood acute lymphoblastic leukemia, and HIV-1 vertical transmission." (PMID 36016321, 2022). "Germline mutations of perforin 1 gene (PRF1) are frequently found in patients with childhood anaplastic large cell lymphoma (ALCL) and acute lymphoblastic leukemia (ALL)." (PMID 31569769, 2019).
anaplastic large cell lymphoma (4 papers, 2019 to 2022). Anaplastic large cell lymphoma (ALCL) is a rare and aggressive peripheral T-cell non-Hodgkin lymphoma, belonging to the group of CD30-positive lymphoproliferative disorders, which affects lymph nodes and extranodal sites. "As such, mutations of PRF1 (encoding for perforin) are frequently found in patients with anaplastic large cell lymphoma (ALCL) and ALL, and mutation of FASLG (encoding for FasL) was observed in lymphoma patients." (PMID 35720306, 2022). "Germline mutations of the perforin gene (PRF1) are often found in patients with childhood anaplastic large cell lymphoma and acute lymphoblastic leukemia." (PMID 34768814, 2021).
Autoimmunity (4 papers, 2018 to 2024). The occurrence of an immune reaction against the organism's own cells or tissues. "Cells within the CD4_Stim2.Th17.1 cluster expressed genes associated with regulatory function (IL10, ITGA2), whereas cells within the CD4_Stim2.Th17.2 cluster expressed proinflammatory effectors (IFNG, IL23R, PRF1), described to be produced by pathogenic Th17 cells in autoimmunity." (PMID 35192548, 2022). "Indeed, splenocytes + lymph node cells from the diseased Prf1−/−PD-1−/− thymocyte recipients generated robust development of autoimmunity when transferred either to Rag−/− or Faslpr × Rag−/− recipients (disease onset: day 18, 22, >22 vs. 13, 18 × 3, 22, respectively; p = NS)." (PMID 29416537, 2018). "Our finding that neither Faslpr × Rag−/− recipients of PD-1−/− HSC, nor recipients of Prf1−/− × PD-1−/− thymocytes were spared from disease suggests that both of these canonical T cell effector pathways are dispensable for LIP-driven autoimmunity in the setting of PD-1 deficiency." (PMID 29416537, 2018).
bladder cancer (4 papers, 2018 to 2025). "in bladder cancer highlighted the presence of distinct subsets of CD4+ T CTL in the tumor microenvironment, expressing different combinations of cytolytic genes (GZMA, GZMB, GZMK, PRF1)." (PMID 37965314, 2023).
diabetes (4 papers, 2008 to 2024). "To assess the functional aspects of cytotoxic T cells, we calculated the cytotoxicity score for CD4 Tcyt and CD8 Tem using cytotoxic genes (PRF1, GZMH, and GZMK) and observed higher cytotoxicity scores in T2D patients compared to non-diabetes." (PMID 39072276, 2024).
gastric cancer (4 papers, 2019 to 2023). A primary or metastatic malignant neoplasm involving the stomach.
head and neck squamous cell carcinoma (4 papers, 2022 to 2025). A squamous cell carcinoma that arises from any of the following anatomic sites: lip and oral cavity, nasal cavity, paranasal sinuses, pharynx, larynx, and salivary glands. "Our data revealed a strong positive correlation between the expression of CCR5, GZMA, IDO1, and PRF1 and CNV in both lung squamous cell carcinoma (LUSC) and head and neck squamous cell carcinoma (HNSC)." (PMID 37646041, 2023).
liver cancer (4 papers, 2020 to 2025). An epithelial or non-epithelial malignant neoplasm that arises from the liver. "Univariate and multivariate Cox regression analyses showed that the expression of CTSV, CXCL8, MKI67 and PRF1 were independent prognostic factors in liver cancer patients." (PMID 35902905, 2022).
pancreatic cancer (4 papers, 2020 to 2025). "Among the genes with the greatest fold change resulting from the CP4 treatment in pancreatic cancer were granzymes, Ctsg and Prf1." (PMID 36451859, 2022). "Furthermore, CALR was significantly correlated with key immunity‐killing molecules, including PRF1, GZMB, and IFNG in pancreatic cancer." (PMID 32508042, 2020).
psoriasis (4 papers, 2023 to 2025). An autoimmune condition characterized by red, well-delineated plaques with silvery scales that are usually on the extensor surfaces and scalp. "Overall, PRF1 has already been implicated in psoriasis pathogenesis through these expression and functional studies, so its presence in the current gene list is not unexpected or novel, but rather corroborates known immune mechanisms in psoriasis." (PMID 41328434, 2025). "Additional Mendelian randomization analysis pinpointed seven marker genes linked to psoriasis: BIN2, CAPN12, CXXC5, KLRC1, KLRD1, PRF1, and SLFN5." (PMID 41328434, 2025). "By integrating single-cell RNA sequencing with MR analysis, we identified seven psoriasis-related genes (BIN2, CAPN12, CXXC5, KLRC1, KLRD1, PRF1, and SLFN5) that are highly expressed in CD4+ T cells." (PMID 41328434, 2025). "Correspondingly, cytotoxic mediators such as PRF1, GZMA, SRGN, and NKG7 were upregulated, paralleling signatures seen in αβ T cells in psoriasis." (PMID 41181116, 2025). "The seven genes span established–emerging–novel tiers: PRF1 and KLRC1/KLRD1 are established in psoriasis immunity; SLFN5 is a recently reported systemic inflammatory marker; BIN2/CXXC5/CAPN12 lack prior links, suggesting novelty." (PMID 41328434, 2025). "KLRC1, KLRD1, PRF1, BIN2, and SLFN5 showed enrichment concentrated in immune-inflammatory modules—including IL-17 signaling, the TNF/NF-κB axis, and innate immune sensor pathways (NOD-, RIG-I-, and Toll-like receptors)—consistent with psoriasis-relevant Th17/innate activation." (PMID 41328434, 2025). "Most notably, CLE and DM lesions were enriched for Th1-skewed CD4+ T cells that, unlike their counterparts in vitiligo, expressed cytotoxic effector molecules including GZMB, GZMK, and PRF1, a population nearly absent in healthy and psoriasis skin (scCODA FDR < 0.1)." (PMID 40894544, 2025). "Higher numbers of PRF1 and GZMB positive cells were detected by immunohistochemistry in lesional skin of AD- and psoriasis patients when compared to non-lesional or healthy skin of respective patients." (PMID 37470818, 2023).
T-cell lymphoma (4 papers, 2014 to 2025). "We reported two cases of HLH, one caused by natural killer (NK)/T-cell lymphoma and another associated with missense variants in the perforin 1 gene." (PMID 36959780, 2023). "Moreover, a PRF1 gene mutation was described in two cases of subcutaneous panniculitis-like T-cell lymphoma." (PMID 24632576, 2014).
vitiligo (4 papers, 2020 to 2025). Generalized well circumscribed patches of leukoderma that are generally distributed over symmetric body locations and is due to autoimmune destruction of melanocytes. "The frequency of CD49a+CD103+CD8+ TRM cells secreting Prf1 and GzmB was increased in the vitiligo lesions of patients, suggesting that the production of IL-2 or IL-15 is enriched in the environment of vitiligo areas." (PMID 39193473, 2024). "The vitiligo case exhibited even higher ISG15 and PRF1, while IFNG, TNF, IL12, and IL15 levels were closer to those in healthy controls." (PMID 33384688, 2020). "In dogs, we found enrichment of T cell gene signatures, with upregulation of IFNG, TNF, PRF1, IL15, CTSW, CXCL10, and CCL5 in both VKH and vitiligo in dogs compared to healthy controls." (PMID 33384688, 2020). "However, the levels of IFNG, PRF1, GZMB and CXCR3, CXCL9, CXCL10, CXCL12, and other cytokines also had an upward trend in the vitiligo group." (PMID 37207234, 2023).
acute myeloid leukemia (3 papers, 2018 to 2020). Acute myeloid leukemia (AML) is a group of neoplasms arising from precursor cells committed to the myeloid cell-line differentiation. "Apart from this extended evasion strategy, an early study involving acute myeloid leukemia (AML) samples revealed that the intrinsic apoptosis resistance associated with this type of cancer relies on an impaired binding of PRF1 to the surface of the tumor cells." (PMID 32466293, 2020). "In a model of acute myeloid leukemia (AML) only wild-type Tregs prevented tumor rejection, compared to Granzyme B knockout (Gzmb−/−) or Perforin1 knockout (Prf1−/−) Tregs." (PMID 29032503, 2018).
aplastic anemia (3 papers, 2011 to 2024). Anemia resulting from bone marrow failure (aplastic or hypoplastic bone marrow).
colon adenocarcinoma (3 papers, 2021 to 2024). "In addition, the positive correlations between ZC3H12C expression and highly connected CD8+ T genes were also visualized, including CD8A, CD8B, GZMA, GZMB, and PRF1 in colon adenocarcinoma and rectum adenocarcinoma." (PMID 38267865, 2024). "The Cancer Genome Atlas (TCGA)-colon adenocarcinoma (COAD) dataset was also analyzed to identify cytotoxic T lymphocyte (CTL) scores using a set of 5 previously reported genes (CD8A, CD8B, GZMA, GZMB, and PRF1) as a surrogate of tumor infiltrating CD8+ T cells." (PMID 38992029, 2024).
Griscelli syndrome type 2 (3 papers, 2015 to 2025). Griscelli syndrome type 2 (GS2) is a rare, inherited condition that affects the skin, hair, and immune system. "Patients were divided into four groups: 1) with PRF1 mutation (n = 46), 2) with UNC13D mutation (n = 38), 3) with STX11/STXBP2 mutation (n = 25) and 4) with Griscelli syndrome type 2/ Chediak–Higashi syndrome (GS2/CHS) diagnosis (n = 44)." (PMID 40263637, 2025). "In 13 out of the 24 (52%) a genetic diagnosis was achieved: PRF1 n = 4 (FHL2), STX11 n = 2 (FHL4), and STXBP2 n = 4 (FHL5), RAB27A n = 2 (Griscelli syndrome type 2), BIRC4 n = 1 (XIAP)." (PMID 30697212, 2018).
Hemophagocytosis (3 papers, 2012 to 2017). Phagocytosis by macrophages of erythrocytes, leukocytes, platelets, and their precursors in bone marrow and other tissues. "Mouse cytomegalovirus infection in perforin-1 knock-out mice induced a lethal condition similar to human HLH characterized by cytopenia with marked inflammatory lesions in the liver and spleen as well as the presence of hemophagocytosis in bone marrow." (PMID 22891066, 2012).
macrophage activation syndrome (3 papers, 2012 to 2025). A complication of rheumatic disease that is caused by excessive activation and uncontrolled proliferation of T lymphocytes and well-differentiated macrophages. "It has been postulated that a genetic association between sJIA and macrophage activation syndrome (MAS) exists via a mutated perforin gene (PRF1) and polymorphism of both MUNC13-4 and interferon regulatory factor 5 (IRF5) genes." (PMID 22235382, 2012).
mastitis (3 papers, 2018 to 2025). Inflammation of breast tissue during lactation or postpartum due to an obstructed duct or infection. "The results demonstrated that, with the exception of PRF1, cows with subclinical mastitis induced by S. chromogenes exhibited significantly higher expression levels of these five cytokines compared to healthy cows." (PMID 41142813, 2025).
Pancytopenia (3 papers, 2017 to 2026). An abnormal reduction in numbers of all blood cell types (red blood cells, white blood cells, and platelets). "In summary, a rare pathogenic mutation in PRF1 gene was identified in our patient with FHL2 disorder, proving the link between PRF1 gene mutations, hepatitis, neurologic manifestations, and pancytopenia in patients with HLH." (PMID 28468610, 2017).
asthma (2 papers, 2010 to 2023). "These causal mediation models revealed that the nasal key drivers of asthma significantly mediate the association between PBMC key drivers in the NK cell module (PRF1 and NKG7) and asthma (FDR = 0.0076 to 0.01)." (PMID 37730635, 2023). "Specifically, we sought to examine causal mediation between PBMC key drivers associated with asthma (PRF1 and NKG7 in the NK cell module; CAPZA2, ATP6AP2, CTSS, and RAB3D from the interleukin module) and nasal key drivers associated with asthma (G3BP1 and INADL from the nasal TCA module)." (PMID 37730635, 2023). "Increased expression of PRF1 in peripheral blood lymphocytes of both allergic and intrinsic asthmatics has been previously reported, and NKG7 was found in a study of publicly available gene expression data to be a marker of severe asthma." (PMID 37730635, 2023).